TMPRSS2 (transmembrane serine protease 2)
Diseases named in the same sentence as TMPRSS2 in open-access papers (continued):
Sharing a sentence is not in itself a finding about the gene and the disease.
COVID-19 (continued). "Very early in the SARS-CoV-2 pandemic, TMPRSS2 was proposed as a potential drug target due to its important role during viral entry, and many clinical studies have been initiated to investigate the efficacy of these drugs in COVID-19 patients." (PMID 35163273, 2022). "Since the first evidence demonstrating the importance of TMPRSS2 in SARS-CoV-2 entry, several studies have been developed in order to investigate the association between genetic polymorphisms in TMPRSS2 and the risk of COVID-19, using genomic databases." (PMID 36423166, 2022). "Here, we analyzed three human genetic polymorphisms belonging to the TMPRSS2 and CCR5 genes in a sample population from Sicily (Italy) to investigate possible correlations with the resistance to viral infection and/or to COVID-19 disease progression as recently described in other human populations." (PMID 36012436, 2022). "Although the lung is the primary target organ for COVID-19, it is necessary to identify TMPRSS2 expression in different cell types of lung which may affect the variable susceptibility to SARS-CoV-2 infection." (PMID 35017320, 2022). "Only sparse expression of ACE2 and TMPRSS2 was noted in testes of COVID-19 infected males." (PMID 36199281, 2022). "SARS-CoV-2, вызывающий COVID-19, получает клеточный доступ через рецептор ангиотензинпревращающего фермента 2 (AПФ2), который связан с трансмембранным белком сериновой протеазы 2 (TMPRSS2)." (PMID 36337014, 2022). "Thus, we systematically reviewed published literature describing genetic features of vulnerability and prognosis for COVID-19, with focus on polymorphisms of ACE2 and TMPRSS2 genes." (PMID 35193695, 2022). "Studies have shown that olfactory epithelial cells express high levels of angiotensin-converting enzyme 2 (ACE2) and transmembrane protease serine 2 (TMPRSS2), which could provide a plausible explanation for COVID-19-related anosmia." (PMID 36071466, 2022). "In addition, cancer has been identified as a personal factor of COVID-19, so the significance of TMPRSS2 expression in pan-cancers is more likely to be connected to the susceptibility of SARS-CoV-2 to tumor patients." (PMID 35281819, 2022). "Besides blocking the cleavage function of TMPRSS2, molecules with the ability to reduce TMPRSS2 expression on host cells also drew attention for anti-COVID-19 research." (PMID 36464706, 2022). "However, therapeutic interventions are also being designed for TMPRSS2 in fighting COVID-19, which makes it a potential target for further investigation." (PMID 36077041, 2022). "Neither the TMPRSS2 rs2070788 nor rs12329760 polymorphisms showed a demonstrable relation with an increased risk of SARS-CoV-2 infection or severity of COVID-19." (PMID 35193695, 2022). "ACE2 and TMPRSS2 play vital roles in the onset, development, and prognosis of SARS-CoV-2 infection, and have both been strongly associated with vulnerability, intensity, and the clinical result of COVID-19." (PMID 35193695, 2022). "Our results identified important TMPRSS2 variations that could be useful to develop high affinity and personalized drugs for treating COVID-19 patients." (PMID 35207518, 2022). "A study showed that COVID-19 could play a significant role by acting on the transmembrane protease, serine 2 (TMPRSS2) gene, which is an important gene in androgens pathways exacerbating alopecia." (PMID 35815081, 2022). "In addition, TMPRSS2 expression was also downregulated in tumor tissues in head and neck cancer patients with COVID-19 compared with matched normal individuals." (PMID 35017320, 2022). "Targeting SARS-CoV-2 entry factors, including TMPRSS2, may be a therapeutic strategy against COVID-19." (PMID 36364238, 2022). "However, while ACE2 and TMPRSS2 have both been suggested as putative therapeutic targets for COVID-19, their circulatory levels have only recently and scarcely been evaluated as potential biomarkers for disease severity and progression." (PMID 35455738, 2022).
COVID-19 (continued). "In this context it is to mention that, despite low ACE2 expression, patients with CVDs have still higher COVID-19 mortality, caused probably by the imbalance between ADAM17 expression required for cleavage of ACE2 for virus uptake, and TMPRSS2, which is required for spike glycoprotein priming." (PMID 36367091, 2022). "The T allele in rs12329760 TMPRSS2 had no protective effect against development of severe COVID-19 symptoms." (PMID 36532428, 2022). "Hence, these molecules can be used as leads for designing the TMPRSS2 targeting drugs for the treatment of COVID-19." (PMID 36064696, 2022). "The SERPINA1 gene is a serine protease inhibitor, alpha-1 antitrypsin, that may protect against COVID-19 by inhibiting TMPRSS2." (PMID 35772218, 2022). "Severe COVID-19 was shown to be related with five SNPs in the TMPRSS2 and neighboring MX1 genes." (PMID 35193695, 2022). "Herein we investigated the prognostic value of serum ACE2 and TMPRSS2 levels in COVID-19 patients, to assess whether their measurement at an early stage of disease may predict associated the need for mechanical ventilation and additional unfavorable outcomes." (PMID 35455738, 2022). "Notably, a study of the Indian population identified a probable association between the TMPRSS2 pVal160Met polymorphism and SARS-CoV2 infection and COVID-19 results." (PMID 35193695, 2022). "In summary, our findings indicate that ACE2 and TMPRSS2 genes not only play crucial roles in the onset, development, and prognosis of SARS-CoV-2 infections, but are all strongly correlated to susceptibility, intensity, and clinical outcomes of COVID-19." (PMID 35193695, 2022). "It has been suggested that another TMPRSS2 inhibitor, bromhexine, presently used as a mucolytic cough suppressant, could be used to treat COVID-19." (PMID 36304162, 2022). "The increased COVID-19 disease severity and death rate in men may be due in part to androgen induction of increased TMPRSS2 and ACE2 expression in men." (PMID 35328625, 2022). "This further supports the potential therapeutic significance of TMPRSS2 in COVID-19." (PMID 36146616, 2022). "Moreover, data regarding polymorphisms in 8 genes (HLA, ABO, ACE1, ACE2, APOE, CCR5, TMPRSS2, and IFITM3) were meta-analyzed in relation to the risk of infection and severity of COVID-19." (PMID 35793369, 2022). "Repurposing the mucolytic drug bromhexine and transcriptional inhibition of TMPRSS2 may also offer some therapeutic options for COVID-19." (PMID 35871712, 2022). "Consistently, the protein level of TMPRSS2 is increased in lungs of COVID-19 patients." (PMID 35301316, 2022). "COVID-19, in congruence with many other viral illnesses like mumps, cytomegalovirus, etc., has been seen to cause thyroid abnormalities owing to its pathogenesis based on ACE2 and TMPRSS2 expression." (PMID 35706733, 2022). "Recently, AAT was proposed to inhibit coronavirus entry by inhibiting the TMPRSS2 protease, and AATD patients may be more susceptible to severe COVID-19." (PMID 35322856, 2022). "Furthermore, sex and TMPRSS2 rs75603675 stand as additional clinically relevant predictors of COVID-19 severity, which were included in the scales." (PMID 35636966, 2022). "According to studies, TMPRSS2 expression is significantly increased in obese patients, which may contribute to the poorer prognosis that is observed during COVID-19 in this patient group." (PMID 35055050, 2022). "Unfortunately, the pathogenic mechanism, based on the cell and tissue tropism involving ACE2 (angiotensin-converting enzyme 2) and TMPRSS2 (transmembrane serine protease 2) in COVID-19, cannot define the systemic multi-organ involvement and neuroendocrine involvement of COVID-19." (PMID 36146578, 2022). "Moreover, we confirmed the association between COVID-19 susceptibility and polymorphisms in the ApoE, ACE1, TMPRSS2, and CCR5 genes." (PMID 35793369, 2022).
COVID-19 (continued). "Since transcription of the TMPRSS2 gene is regulated by androgen receptors, their antagonists may be considered as a therapeutic option against COVID-19 due to its role in downregulating TMPRSS2." (PMID 35632833, 2022). "snRNA-seq from lungs of fatal COVID-19 cases further supports the low expression of ACE2/TMPRSS2." (PMID 35492217, 2022). "Patients undergoing ADT have been reported to express lower levels of TMPRSS2, and may be less affected by COVID-19." (PMID 35163273, 2022). "Androgen-deprivation therapy (ADT) accompanied with viral inhibitorsreduces the expresion of TMPRSS2 and could be utilised to treat COVID-19 patients particularly male." (PMID 36299504, 2022). "The human serine protease serine 2 (TMPRSS2) is a transmembrane protease of host cells; it cleaves and activates the S protein of SARS-CoV-2 to bind with ACE2 on the initiated stage of the viral infection and reveals that TMPRSS2 is a suitable target for COVID-19 therapy." (PMID 35496320, 2022). "Based on these facts, it is plausible to state that because ACE2, TMPRSS2, and CXCL10 are commonly contributing molecules in both the pathogenesis of SARS-CoV-2 and PRAD, men could be more susceptible to acquiring COVID-19." (PMID 36239108, 2022). "Therefore, targeting the TMPRSS2 is a rational approach to manage the spread and infection caused by SARS-CoV-2 and to treat the COVID-19 patients." (PMID 33786727, 2022). "Thus, some host genetic factors associated with the development of severe COVID-19 include the polymorphism of ACE2, TMPRSS2, and other transmembrane proteins." (PMID 35062298, 2022). "Using WES data, we focused on nine genes that have been reported to be involved in the SARS-CoV-2 entry pathway (ACE2, RAB7B, ADAM17, TMPRSS2), host immune response (IFNAR2, TYK2), and/or were previously shown to be associated with COVID-19 outcomes (DPP9, LZTFL1, SLC6A20)." (PMID 36292769, 2022). "Therefore, researchers are searching for TMPRSS2 inhibitors that can be used for the treatment of COVID-19." (PMID 35807455, 2022). "Spike protein (S protein) of SARS-CoV-2 mediates host cell entry via angiotensin-converting enzyme 2 (ACE2) and transmembrane serine protease 2 (TMPRSS2), targeting of which could serve as an important therapeutic strategy for COVID-19." (PMID 36187008, 2022). "TMPRSS2 is considered a potential target for COVID-19 therapy." (PMID 35327350, 2022). "The ACE2, TMPRSS2, and Furin could be important biomarkers to provide insights into pre-COVID-19 and post-COVID-19 management." (PMID 35160229, 2022). "Approved drugs that are known to inhibit TMPRSS2 may be suitable for off-label use and repurposing in COVID-19 prevention and therapy." (PMID 35804152, 2022). "Apparently, targeting the TMPRSS2 as well as Mpro is a better option for the treatment of COVID-19." (PMID 35836239, 2022). "Our findings support the hypothesis that TMPRSS2 may contribute to the outcome of COVID-19 in older individuals." (PMID 36423166, 2022). "ACE2, Furin and TMPRSS2 together play a pivotal role in COVID-19 pathophysiology." (PMID 35160229, 2022). "Using platelets from healthy volunteers and COVID-19 patients, they showed that human platelets expressed hACE2 and TMPRSS2, and platelets from COVID-19 patients had notable hyperactivity and mean platelet volumes correlating with decreased overall platelet counts." (PMID 36547234, 2022). "In addition to ACE2, TMPRSS2 and TLRs, other genetic elements like Apolipoprotein E (APOE) have been reported to increase risk of severe COVID-19." (PMID 35956081, 2022). "Our data adds to considerable literature on ACE2 and TMPRSS2 in COVID-19 pathogenesis." (PMID 35996506, 2022). "Moreover, we believe that is the first report, in any cell type, demonstrating that IAV modifies both ACE2 and TMPRSS2 mRNA expression and post-transcriptional regulation in a manner consistent with priming for more severe COVID-19 manifestations." (PMID 33419885, 2021).
COVID-19 (continued). "In the meantime, other TMPRSS2 inhibitors with improved potency against COVID-19 have appeared." (PMID 34071206, 2021). "Regarding a genetic predisposition to a serious course of COVID-19, we did not observe any association with the analyzed TMPRSS2 variants." (PMID 33968142, 2021). "Targeting TMPRSS2 by a protease inhibitor could in fact be an anti-COVID-19 strategy blocking SARS-CoV-2 cell infection." (PMID 34399734, 2021). "The use of essential oils that have both the function of suppressing the secretion of cytokines as well as suppressing the expression of ACE2 and TMPRSS2 could be one of the promising methods to prevent and treat COVID-19." (PMID 34445619, 2021). "TMPRSS2 was upregulated in the distal tubule of all the severe COVID-19 patients’ kidney samples." (PMID 34136484, 2021). "Thus, our findings do not support the postulated protective role of enzalutamide in treating COVID-19 through reducing TMPRSS2 expression in lung cells." (PMID 33558541, 2021). "Considering that the activated androgen receptor regulates transcription of TMPRSS2 gene, androgen hormone receptors signaling antagonists could be explored as treatment strategies against COVID-19 for their role in downregulating TMPRSS2." (PMID 34391321, 2021). "Given the critical role of ACE2 and TMPRSS2 in SARS-CoV-2 infection, the higher expression of ACE2 and TMPRSS2 may contribute to the higher vulnerability to COVID-19 in these tissues." (PMID 34094637, 2021). "This is relevant for the prevention of severe COVID-19-related illness, given that ACE2 and TMPRSS2 have been identified as crucial components of the molecular machinery used by SARS-CoV-2 to infects cells." (PMID 34684358, 2021). "Similar to aprotinin, camostat has shown promise in the reduction of influenza viral replication, and the repurposing of this drug for COVID-19 treatment is currently underway given its potent inhibitory action against the virus-activating host cell protease TMPRSS2." (PMID 34072295, 2021). "The expression of the TMPRSS2 gene is promoted by testosterone hormone, which might explain the severity of COVID-19 in men due to facilitating the entry of SARS-CoV-2." (PMID 34568081, 2021). "Neither TMPRSS2 rs2070788 nor rs12329760 polymorphisms were related to SARS-CoV-2 infection risk or severity of COVID-19." (PMID 33968142, 2021). "Docking evidence indicated that baicalin binds to TMPRSS2 and leads to the inhibition of COVID-19." (PMID 34068970, 2021). "Since testosterone level decreases with age, a higher level of the hormone in young and middle age men may upregulate TMPRSS2 and thus contribute to the higher sex ratio for COVID-19 mortality before the sixth decade." (PMID 33550276, 2021). "Furthermore, we found that TMPRSS2 and kidney injury makers were upregulated in COVID-19 patients’ renal tubular cells." (PMID 34136484, 2021). "The upregulated TMPRSS2 expression in response to androgens could explain the sex-discrepancy in COVID-19 outcomes." (PMID 34595175, 2021). "Both high and low testosterone levels can favor severe COVID-19, as high testosterone levels may upregulate TMPRSS2, facilitating the entry of SARS-CoV-2 into host cells." (PMID 33920748, 2021). "Again, COVID-19 patients with DM also showed higher levels of TMPRSS2 expression." (PMID 33962629, 2021). "The renal tropism of SARS-CoV-2 revealed by the high expression of ACE2 and TMPRSS2 in the kidney may explain the renal injury in COVID-19 patients." (PMID 33401657, 2021). "TMPRSS2 is significantly decreased in the lung of COVID-19 patients." (PMID 34168096, 2021). "Whether BA also disturbs the catalytic activity of TMPRSS2 or blocks the migration of activated neutrophils to the lung tissue in severe cases of COVID-19 would be interesting to investigate." (PMID 34869231, 2021).
COVID-19 (continued). "Considering the connection between androgens and TMPRSS2 expression, especially in the lungs, the predominance in the number of COVID-19 deaths among males may be partially explained by high androgen levels and hence sustained TMPRSS2 expression." (PMID 34001144, 2021). "Although the tissue locations of ACE2+ TMPRSS2+ cells might partly explain the signs and symptoms of COVID-19, other indirect conditions might also be involved, which include social, economic, and behavioral differences." (PMID 34094637, 2021). "We posit that the effects of androgens and androgen receptor signaling on TMPRSS2 and immune response could potentially contribute to the increased severity of COVID-19 in prostate cancer patients." (PMID 33915795, 2021). "Moreover, cells in the olfactory epithelium express angiotensin-converting enzyme 2 (ACE2) and transmembrane protease, serine 2 (TMPRSS2) protein receptors that are needed for the progression of COVID-19 in the body." (PMID 34692340, 2021). "Initial whole genome analysis of 322 COVID-19 patients in a Chinese population observed a decreasing allele frequency of the TMPRSS2 rs12329760 variant among patients with severe disease compared with patients with mild COVID-19, indicating the importance of TMPRSS2 in COVID-19." (PMID 34001248, 2021). "It has been proposed that the gender differences in COVID-19 cases may be related to cigarette smoking, where smoking is generally more common among men than in women, and smoking may upregulate TMPRSS2/ACE2 in the lung." (PMID 34832534, 2021). "Results showed that a model including age, systemic arterial hypertension, diabetes, obesity and TMPRSS2/ACE2 minimized the Akaike Information Criteria (AIC = 97.11), suggesting that TMPRSS2/ACE2 ratio outperforms ACE2 expression predictive power to model COVID-19 respiratory outcome in this cohort." (PMID 33958627, 2021). "With respect to COVID-19 susceptibility in NHPs, orthologues of human TMPRSS2 can be found across many NHP species; among humans, polymorphisms in TMPRSS2 have been postulated as an explanation for global population differences in COVID-19 infection rates and disease severity." (PMID 34359172, 2021). "The induction of TNF-α by SARS-CoV-2 infection and the subsequent upregulation of ACE2 and TMPRSS2 in cardiomyocytes may partially explain the high incidence of cardiac involvement in hospitalized COVID-19 patients." (PMID 34576032, 2021). "Blocking viral entry by targeting S/ACE2 interaction or TMPRSS2-mediated priming may constitute an effective treatment strategy for COVID-19." (PMID 34071060, 2021). "Moreover, different therapeutic modalities such as dexamethasone, nitric oxide, and chloroquine, which are effective in managing COVID-19, are reported to have anti-androgenic effects and suppression of TMPRSS2." (PMID 34568081, 2021). "Neither TMPRSS2 rs2070788 nor rs12329760 polymorphisms were related to SARS-CoV-2 infection risk or severity of COVID-19 in our German cohort." (PMID 33968142, 2021). "In general, these findings unveil TMPRSS2 as a bond connecting prostate cancer and COVID-19, paving the way for repurposing conventional drugs that have few on-target side effects for treating COVID-19 based on androgen suppression and TMPRSS2 protease inhibition." (PMID 34001144, 2021). "Among them, glycyrrhizin and glycyrrhetinic acid interact with ACE 2, spike protein, host transmembrane serine protease 2 and 3-chymotrypsin-like cysteine protease to alleviate the common symptoms of COVID-19 patients, such as pulmonary inflammation and liver and kidney injury." (PMID 34899289, 2021). "However, its harmful effects in COVID-19 are due to augmentation of transmembrane protease serine 2 (TMPRSS2), which is essential for cleaving and activating SARS-CoV-2 spike protein during acute SARS-CoV-2 infection." (PMID 34568081, 2021). "TMPRSS2 overexpression was detected in several tissues, which may also favor the appearance of a number of extra-pulmonary COVID-19 effects." (PMID 33479353, 2021).